USP4 (ubiquitin specific peptidase 4)
Description:
Deubiquitinating enzyme that removes conjugated ubiquitin from target proteins. Deubiquitinates PDPK1. Deubiquitinates TRIM21. Deubiquitinates receptor ADORA2A which increases the amount of functional receptor at the cell surface. Deubiquitinates HAS2. Deubiquitinates MAVs leading to maintain MAVS protein stability, resulting in increased production of type I interferons (IFN-I) and enhanced antiviral innate immune responses against viral infections. Deubiquitinates RHEB in response to EGF signaling, promoting mTORC1 signaling. May regulate mRNA splicing through deubiquitination of the U4 spliceosomal protein PRPF3. This may prevent its recognition by the U5 component PRPF8 thereby destabilizing interactions within the U4/U6.U5 snRNP. May also play a role in the regulation of quality control in the ER.
Synonyms: UNP; UNPH
Tractability: PROTAC: UniProt records ubiquitination sites on it; ubiquitination databases record sites on it; its protein half-life has been measured; a small molecule that binds it is known.
Target class: Cysteine protease; Cysteine protease CA clan; Protease; Enzyme; Cysteine protease C19 family
Gene: Protein-coding gene on chromosome 3 (49,277,144 to 49,340,712, reverse strand). Ensembl gene ENSG00000114316.
Subcellular location: Cytoplasm; Nucleus
Subcellular location (Human Protein Atlas): Nucleoplasm; Basal body; Cytosol; Vesicles
Pathways (Reactome):
Signal Transduction: Regulation of TNFR1 signaling; TNFR1-induced NF-kappa-B signaling pathway; TNFR1-induced proapoptotic signaling
Metabolism of proteins: Ub-specific processing proteases
Gene Ontology:
Molecular function: adenosine receptor binding; cysteine-type deubiquitinase activity; identical protein binding; protein binding
Biological process: negative regulation of protein ubiquitination; positive regulation of TORC1 signaling; protein deubiquitination; protein localization to cell surface; regulation of protein stability; spliceosomal tri-snRNP complex assembly
Cellular component: cytoplasm; cytosol; nucleoplasm; nucleus; lysosome
Genetic constraint (gnomAD): Loss-of-function variants: 67 observed, 113.57 expected, observed/expected ratio (o/e) 0.59, 90% interval 0.48 to 0.72. The upper end of that interval is the gene's LOEUF score, 0.72, which puts it in group 2 of 6, group 1 being the genes least tolerant of losing a copy. Missense variants: 982 observed, 1,183.7 expected, observed/expected ratio (o/e) 0.83, 90% interval 0.79 to 0.88. Synonymous variants: 393 observed, 443.35 expected, observed/expected ratio (o/e) 0.89, 90% interval 0.81 to 0.96.
Homologues: Orthologues: chimpanzee USP4 (99% identical), macaque USP4 (96% identical), dog USP4 (95% identical), pig USP4 (95% identical), mouse Usp4 (91% identical), rat Usp4 (90% identical), rabbit USP4 (88% identical), guinea pig USP4 (88% identical), tropical clawed frog usp4 (69% identical). Paralogues in human: USP15 (60% identical), USP11 (44% identical), USP19 (27% identical), USP32 (26% identical), USP6 (23% identical), USP8 (22% identical), USP31 (22% identical), USP9X (20% identical), USP9Y (20% identical), USP24 (20% identical), USP43 (20% identical), USP2 (17% identical), and 59 more.
Diseases named in the same sentence as USP4 in open-access papers:
USP4 is named in the same sentence as 81 diseases in open-access papers, as found by Europe PMC text mining. Sharing a sentence is not in itself a finding about the gene and the disease. The quoted sentences say what the papers report.
breast carcinoma (30 papers, 2014 to 2025). "A study demonstrated that AKT-mediated phosphorylation of USP4 was associated with poor prognosis in breast cancer patients." (PMID 34177595, 2021). "Taken together, these results suggest that mutations of USP4 L301R, S315C, and R559W may play a role in the pathogenesis of breast cancer, probably through destabilizing BRCA1." (PMID 38734703, 2024). "This phenomenon suggests that these mutation types have a dominant negative effect, and BRCA1 could still be downregulated in the breast cancers bearing these USP4 mutations." (PMID 38734703, 2024). "Therefore, we searched TCGA database and a series of USP4 mutations were found in gynecologic cancers including breast cancer, ovarian cancer and cervical cancer." (PMID 38734703, 2024). "High USP4 expression is associated with the poor prognosis of patients with breast cancer." (PMID 36993976, 2023). "Together, these results demonstrate that the FBXO3-USP4-Twist1 axis is critically important in p110αH1047R-induced cell migration and tumor metastasis, and that elevated expression of PIK3CA/FBXO3/USP4/Twist1 is associated with poor clinical outcomes of breast cancer patients." (PMID 38134227, 2023). "Moreover, USP4 expression was associated with decreased proliferation in two HER2-negative breast cancer cell lines (MCF7 and BT549)." (PMID 36627894, 2022). "In breast cancer, higher expression of USP4 is associated with distant metastasis." (PMID 33681193, 2021). "In contrast, the scenario in breast cancer is distinct, with researchers observing a significant downregulation of USP4 expression relative to paired normal breast tissue samples." (PMID 39393052, 2024). "In breast cancer, USP4 adopts a tumor-suppressive role, inhibiting cell growth through the upregulation of PDCD4." (PMID 39393052, 2024). "Consistent with our assumption, we observed decreased USP4 expression in 63% of the breast cancer tissues, and a positive correlation between USP4 and BRCA1 was found." (PMID 38734703, 2024). "Representative images as shown, USP4 expression was significantly downregulated in the breast cancer tissues compared with human normal breast tissues and the corresponding adjacent tissues." (PMID 38734703, 2024). "FBXO3 can bind to and stabilize USP4, leading to Twist1 protein stabilization and increased breast cancer cell migration and tumor metastasis." (PMID 38134227, 2023). "USP4 (a cysteine protease) has been identified as the downstream target of DNPEP in the PAK5/DNPEP/USP4 regulatory axis in breast cancer." (PMID 36993976, 2023). "In a previous study on breast cancer, USP4 was shown to promote TGF-β signaling and to cooperate with AKT signaling to promote cancer cell EMT, migration, and invasion." (PMID 37949874, 2023). "Clinically, elevated expression of p110α/FBXO3/USP4/Twist1 is associated with poor overall survival (OS) and recurrence-free survival (RFS) of breast cancer patients." (PMID 38134227, 2023). "In this study, we demonstrate that USP4 is a key downstream effector in PI3K-induced breast cancer metastasis." (PMID 38134227, 2023). "Knockdown of either FBXO3 or USP4 leads to significant inhibition of PI3K-induced breast cancer metastasis." (PMID 38134227, 2023). "It has been reported that USP4 expression was decreased in breast cancer tissue samples compared to paired normal breast tissues." (PMID 36627894, 2022). "By contrast, USP4 was reported to play a tumor-suppressing role in breast cancer 44 and lung cancer." (PMID 34335955, 2021). "USP4 contextually shows paradoxical tumor-promoting and -suppressing effects in breast cancer growth." (PMID 34575114, 2021). "TGF-β-induced migration of MDA-MB-231 cells is inhibited by USP4 knockdown and PI K–AKT signalling inhibitors, indicating that phosphorylation of USP4 plays a critical role in AKT-mediated breast cancer cell migration." (PMID 34177595, 2021). "A decrease in USP4 expression is found in breast cancer tissues, indicating a tumor-suppressive role for USP4." (PMID 34575114, 2021).
breast carcinoma (continued). "The role of USP4 in breast cancer progression is complicated and contradictory which depends on different upstream and downstream signaling pathways." (PMID 32669974, 2020). "In breast cancer cell lines, USP4 was initially found to be phosphorylated by pAKT and exported from nucleus to deubiquitinate and stabilize TβRI and activate downstream TGF-β signaling pathway." (PMID 32669974, 2020). "Similar to breast cancer, USP4 can also be negatively regulated by miR-148a which implied the potential therapeutic role of miR-148a in liver cancer." (PMID 32669974, 2020). "This study suggests that Akt activation in breast cancer cells induces USP4 to relocate and stabilize TβRI in the plasma membrane, and thereby enforces TGF-β-induced pro-tumorigenic responses." (PMID 24756567, 2014). "AKT activation is associated with poor prognosis in breast cancer and inhibiting USP4 suppresses AKT-mediated breast cancer cell migration." (PMID 25606592, 2014). "Depletion of USP4 in highly metastatic MDA-MB-231 breast cancer cells leads to the depletion of EMT markers and TGFβ-induced migration in vitro, and in vivo in a zebrafish xenograft invasion metastasis model." (PMID 25606592, 2014). "For instance, it would be interesting to develop inhibitors for USP4/11/15 and examine their potentials for anti-invasive and anti-metastatic roles in aggressive human cancers such as breast cancer and glioblastoma." (PMID 24756567, 2014). "In this respect it is important to note that while functional linkage of USP4 to the TGF-β/SMAD pathway was shown by employing a breast cancer model, USP15 can enhance the tumorigenic effect of TGF-β in glioblastoma." (PMID 24756567, 2014). "USP4 has been reported to have higher expression levels in metastatic breast carcinomas as compared with the normal breast samples." (PMID 25606592, 2014). "Moreover, USP4 is low expressed in human breast cancer tissues and its low expression correlates with poorer survival of patients." (PMID 38734703, 2024). "High USP4 expression was observed in low-grade cancers, and vice versa, indicating that lower USP4 expression might correlate with a poorer differentiation status and more aggressive phenotype in breast cancer patients." (PMID 38734703, 2024). "Based on its role in stabilizing BRCA1, we speculate that USP4 mutations could exist and be a mechanism for the downregulation of BRCA1 in those breast cancers." (PMID 38734703, 2024). "Consistently, Western blot analysis of USP4 and BRCA1 in multiple breast cancer cell lines including luminal and triple negative breast cancers, and normal human mammary epithelial cells further implied that expression of USP4 and BRCA1 is positively correlated." (PMID 38734703, 2024). "Activation of PI3K signaling (including both expression levels of the PI3K catalytic subunit p110α or the up-regulated ERK phosphorylation) was positively correlated with cell migration capacity as well as FBXO3/USP4/Twist1 protein levels in breast cancer cell lines examined." (PMID 38134227, 2023). "Interestingly, USP4 was reported to exhibit a tumor suppressor role in certain cancers, including breast cancer and head and neck squamous cell carcinoma." (PMID 37949874, 2023). "Taken together, this study reveals that the FBXO3-USP4-Twist1 axis is pivotal in PI3K-mediated breast tumor metastasis and that FBXO3/USP4 may be potential therapeutic targets for breast cancer treatment." (PMID 38134227, 2023). "Notably, IHC analyses of human breast TMA showed that USP4 was positively correlated with the expression of FBXO3 or Twist1 in breast cancer samples." (PMID 38134227, 2023). "USP4 is also negatively regulated by miR-553 in breast cancer, and this inhibition could be reversed by circBMPR2, which acts as a sponge to prevent miR-553 associating with USP4 mRNA." (PMID 33681193, 2021). "Moreover, knockdown of USP4 facilitated the proliferation, migration, and invasion of breast cancer cells, as well as tamoxifen resistance." (PMID 33681193, 2021).
breast carcinoma (continued). "Therefore, phosphorylation is essential for stabilizing and maintaining the protein levels of USP4 and plays a potential role in breast cancer pathogenesis." (PMID 34177595, 2021). "Phosphorylated USP4 was found in cytoplasm and cell membrane in breast cancer cells." (PMID 32669974, 2020). "Expression of USP4 was also significantly reduced in breast cancer tissue." (PMID 31936290, 2020). "Higher expression of USP4 is regulated by several molecules in breast cancer." (PMID 32669974, 2020). "Moreover, miR-553 can also inhibit USP4 expression in breast cancer tissues and the effect can be inversed by ectopic circBMPR2." (PMID 32669974, 2020). "Also, HDAC2 knockdown in breast cancer cells leads to inhibition of proliferation and USP4 knockout results in the retarded growth of mouse embryonic fibroblasts (MEF)." (PMID 30071870, 2018). "We observed that silencing of USP4 in breast cancer cells led to a small but significant increase in the amount of hyaluronan secreted into the culture media, which is consistent with an importance of Lys190 and possibly monoubiquitination for the regulation of hyaluronan synthesis by HAS2." (PMID 28604766, 2017). "Aberrant protein degradation may be important in this cancer, as three of the 14 mutated genes (USP4, USP31, and ZNRF4) in the breast cancer are involved in the ubiquitin–proteasome pathway." (PMID 26432421, 2015). "Additionally, two studies indicated that USP4 downregulation might also mediate a tumor-suppressing role in breast cancer." (PMID 33681193, 2021). "In addition, USP4 expression could be upregulated by CircBMPR2-miR-553 to suppress breast cancer resistance to tamoxifen." (PMID 32549341, 2020). "Studies have reported that USP4 could inhibit breast cancer cell growth by upregulating PDCD4." (PMID 30335615, 2018). "Indeed, analysis in malignant breast cancer cells revealed that USP4 could regulate TGF-β-induced EMT, migration in vitro and stimulate TGF-β/SMAD signaling-dependent breast cancer invasion and metastasis in vivo." (PMID 24756567, 2014). "USP4 positively regulates the stability and function of BRCA1 through de-ubiquitination, and plays important role in the suppression of breast cancer." (PMID 38734703, 2024). "To further validate this finding, we analyzed the correlation between USP4 expression and the tumor node metastasis (TNM) stage in a larger-scale array of 226 breast cancer tissue samples." (PMID 38734703, 2024). "We next correlated the expression of commonly shared identified genes; BIRC6, MAP3K2, USP4 and SMG1 with immune populations in different breast cancer subtypes." (PMID 38710724, 2024). "Only 0.5% of the total transcriptome correlated with the presence of Tregs and only four transcripts, BIRC6, MAP3K2, USP4 and SMG1, were commonly shared among the different breast cancer subtypes." (PMID 38710724, 2024). "Thus, targeting FBXO3/USP4 may represent a new therapeutic strategy for breast cancer treatment." (PMID 38134227, 2023). "A series of tumors, including breast cancer, colorectal cancer, lung cancer, brain metastatic lung adenocarcinoma, glioblastoma (GBM), melanoma, HCC, and adrenocortical carcinoma, overexpress USP4." (PMID 33681193, 2021). "MiR-148a and miR-27b were reported to destabilize USP4 mRNA by targeting its 3′-UTR in HCC, breast cancer, and liver fibrosis." (PMID 33681193, 2021). "USP4 was found to interact with and stabilize programmed cell death 4 (PCD4) that is involved in the inhibition of breast cancer cell proliferation." (PMID 33681193, 2021). "The therapeutic effects of DUB inhibitors such as USP1, USP4, USP7, USP14 and USP33 have been confirmed in prostate cancer, lung cancer, breast cancer and hematological malignancies." (PMID 34179009, 2021). "USP4 has thus been proposed as an important determinant of crosstalk between TGFβ and AKT signaling in breast cancer." (PMID 25606592, 2014).
breast carcinoma (continued). "Taken together, our study suggest USP4 is a key regulator of BRCA1 and dysregulation could play an important role in the pathogenesis of breast cancer." (PMID 38734703, 2024). "However, it is noteworthy that divergent roles of USP4 have been identified in other cancer types, such as head and neck squamous cell carcinoma (HNSCC) and breast cancer, where USP4 acts as a tumor suppressor." (PMID 39393052, 2024). "This study reveals a non-canonical function of the E3 ubiquitin ligase FBXO3 in PI3K-induced breast cancer metastasis, showing that FBXO3 binds to and protects USP4 from aspartyl aminopeptidase (DNPEP)-mediated degradation, resulting in Twist1 protein stabilization and increased tumor metastasis." (PMID 38134227, 2023). "Mainly USP4, USP7, USP22, UCHL1, UCHL5, and OTUB1 could be used as biomarkers for each type of cancer such as EOC, breast cancer, melanoma, cervical cancer, and colorectal cancer." (PMID 37107644, 2023). "USP4 directly deubiquitylates TGF-β receptor I to induce the phosphorylation of Smad2 and up-regulate matrix metalloproteinase (MMP)-9, thereby facilitating cell migration and invasion of breast cancer cells." (PMID 38134227, 2023). "Additionally, AKT-induced phosphorylation of USP4 is required for maintaining the stability of USP4, thereby enhancing TGF-β-induced pro-tumorigenic responses in breast cancer cells." (PMID 34177595, 2021). "However, USP4 is phosphorylated upon IGF-I and TGF-β induction, and depletion of USP4 reduces IGF-I-Myr-AKT-induced migration in MDA-MB-231 breast cancer cells." (PMID 33946990, 2021). "Inhibition of USP11, USP4 and USP15 blocks TGFβ-mediated EMT and invasion in breast cancer." (PMID 25606592, 2014). "Decreased BRCA1 and USP4 was observed in 59% (134 of 226) and 63% (143 of 226) of breast cancer respectively, whereas only 10% (23 of 226) and 8% (18 of 226) exhibited high expression, suggesting that both BRCA1 and USP4 are downregulated in human breast cancers." (PMID 38734703, 2024). "Finally, USP4 was reported to interact with and be degraded by aspartyl aminopeptidase (DNPEP), a metalloenzyme belonging to the M18 aminopeptidase family, resulting in suppression of its oncogenic role in breast cancer." (PMID 33681193, 2021). "The result demonstrated that the expression of USP4 was much lower in stage III cases than that in other stages, suggesting a negative relationship between USP4 expression and breast cancer TNM stage." (PMID 38734703, 2024). "Strikingly, three USP4 mutants from breast cancer, namely L301R, S315C, and R559W, failed to upregulate endogenous BRCA1 protein level, whereas most of other mutants could still efficiently promote the accumulation of BRCA1 like USP4 WT." (PMID 38734703, 2024).